IL6 (interleukin 6)
Diseases named in the same sentence as IL6 in open-access papers (continued):
Sharing a sentence is not in itself a finding about the gene and the disease.
melanoma (continued). "Five molecules show a significantly (p < 0.05) different expression in melanoma vs. the controls, namely, IL-1b, IL-6, IP-10, PDGF-BB, and RANTES." (PMID 33302400, 2020). "Taken together, these data suggest that suppression of IL-6 expression plays a crucial role in the inhibitory effect of ATF3-overexpressing HDFs on melanoma cell proliferation and migration." (PMID 32373541, 2020). "Combined blockade of IL6 and PD-L1 signaling achieves synergistic antitumor immune responses in colon carcinoma and murine melanoma models." (PMID 32403421, 2020). "Studies have also shown that tumor‐derived IL‐6 promotes the polarization of M2 macrophages in melanoma." (PMID 32931642, 2020). "In accordance, IL-6 is commonly elevated in inflammatory arthritis following ICIs therapy as demonstrated in several type of cancer (e.g. malignant melanoma)." (PMID 33162990, 2020). "Taken together, these data suggest that decreased production of IL-6 in ATF3-overexpressing HDFs contributes to inhibition of melanoma cell proliferation and migration by blocking the STAT3 pathway." (PMID 32373541, 2020). "Plasma increased IL-6 levels have been correlated with poor overall survival in melanoma patients treated with ICIs-based immunotherapy." (PMID 33162990, 2020). "Targeted inhibition of IL-6, for instances, enhanced the efficacy of anti-PD-1 therapy in pancreatic cancer models and in melanoma-bearing mice." (PMID 31316109, 2019). "This is an interesting observation since IL‐6 has been previously shown to drive melanoma metastasis via its ability to promote melanoma cell invasion." (PMID 30582770, 2019). "Here we show that human melanoma tumors produce both IL-6 and IL-8 and that high levels of these cytokines in the circulation are associated with decreased overall survival." (PMID 31781510, 2019). "Both IL-6 and IL-8 can act directly on melanoma cells or can recruit immunosuppressive and proangiogenic cells such as MDSCs, regulatory T cells (Tregs), and tumor-associated macrophages (TAMs)." (PMID 31781510, 2019). "We have previously reported the existence of an IL‐6/WNT5A positive feedback loop in parental BRAFi‐sensitive melanoma cells that is related to their migratory and invasive properties." (PMID 30582770, 2019). "Our results reveal that Wnt5a stimulates melanoma cells to secrete IL-6, IL-8, IL-11, MCP-1, IL-6sR, and sTNFRI." (PMID 31510045, 2019). "Although we observed an increase in Rac1 activity in BRAFi‐R melanoma cells, we did not observe a statistically significant reduction in the elevated Rac1 activity of BRAFi‐R melanoma cells after combined treatment with an IL‐6 Ab and Box5." (PMID 30582770, 2019). "Although IL-6 can have anti-tumor effects in the early phases of melanoma progression, in the later stages, IL-6 promotes tumor angiogenesis and recruits immunosuppressive myeloid cells to the tumor microenvironment." (PMID 31781510, 2019). "We noticed that individual exposure to Box5 or an IL‐6 Ab caused reduced migration and invasion of HTB63‐R and A375‐R melanoma cells by 25–30% in comparison with their vehicle controls." (PMID 30582770, 2019). "With the exception of IL-6, the level of these cytokines in primary melanoma tumors also significantly correlated with that of Wnt5a (red symbols)." (PMID 31510045, 2019). "In this study, we demonstrate for the first time that the induction of BRAFi‐R in melanoma cells results in a prominent amplification of IL‐6 secretion along with elevated WNT5A expression." (PMID 30582770, 2019). "Through an autocrine loop, including the activation of STAT3, IL-6 signaling contributes to survival and proliferation of melanoma cells, increases the metastatic potential, and facilitates immune evasion." (PMID 31269655, 2019). "We then compared the expression of IL-6 and IL-8 in melanoma tumors to the corresponding plasma concentrations and the frequency of circulating MDSCs." (PMID 31781510, 2019).
melanoma (continued). "IL-6 was shown to initiate the secretion of WNT-5a in melanoma cells and human bone marrow stromal cells, respectively." (PMID 32195204, 2019). "This study provides further support for identifying potential therapeutics targeting IL-6, IL-8, and MDSCs to improve melanoma treatments." (PMID 31781510, 2019). "On the other hand, in Me45 melanoma cells visfatin increased oxidative stress and ROS due to its pro-inflammatory action in increasing production of interleukins IL-6 and IL-8." (PMID 31511067, 2019). "Altogether, our study demonstrates that the development of BRAFi‐R in melanoma cells triggers a significant increase in IL‐6 secretion along with elevated WNT5A protein expression." (PMID 30582770, 2019). "In this context, IL-6 is central in melanoma development and also enhances the IL-10 production via STAT-3-dependent signaling." (PMID 31750245, 2019). "Several studies, with the majority of them in ipilimumab-treated melanoma patients, have reported various predictive biomarkers for irAEs, such as level of circulating IL-6, autoantibodies, blood-cell counts, T-cell repertoire, and gut microbiome." (PMID 31816940, 2019). "Our present study suggests a possible therapeutic potential for a future IL‐6/WNT5A‐based antimetastatic approach for BRAFi‐R melanoma patients." (PMID 30582770, 2019). "In another study, IL‐6 levels were higher in thyroid cancer cell lines with inherent apoptosis resistance to RAF‐MAPK inhibitors than RAF‐MAPK inhibitor‐sensitive melanoma and colon cancer cell lines." (PMID 30582770, 2019). "High levels of IL6 dramatically promoted tumor invasion and metastasis of murine melanoma by upregulation of transcription activity of STAT3 and production of STAT3-dependent MMP9 in tumor cells." (PMID 31680949, 2019). "In one trial, BRMS1, a metastasis suppressor, inhibited melanoma angiogenesis by suppressing NF-kB activity and IL-6 expression via induction of ING4." (PMID 30643005, 2019). "This study focused on preventing the increased invasive migration of BRAFi‐R melanoma cells; however, our combined treatment with an IL‐6 antibody and Box5 also restored the sensitivity of these cells to the BRAF inhibitor PLX4032." (PMID 30582770, 2019). "And then IL-6 activated oncogenic STAT3 in melanoma cells and increased expression of prosurvival genes, such as Bcl-2, Bcl-xl." (PMID 30800130, 2019). "Specifically, anti-melanoma CD8+ T cells overexpress PD-1 in the presence of large amounts of tumor-specific cytokines such as IL-6, a well-described regulator of Bcl-6 expression." (PMID 30745900, 2019). "Together these results indicate an important role for IL-6 and IL-8 in melanoma patients in which IL-6 potentially expands peripheral MDSCs and IL-8 recruits these highly immunosuppressive cells to the tumor microenvironment." (PMID 31781510, 2019). "This study focuses on the role of IL-6 and IL-8 in the expansion and recruitment of MDSCs and their resulting impact on clinical outcomes in melanoma patients." (PMID 31781510, 2019). "IPA analyses of transcriptomic expression profiles indicated TNF, the MMP-2 and IL-6 pathways as the most significantly upstream regulators, strongly suggesting them as possible key modulators of the melanoma cell aggressiveness." (PMID 30591049, 2018). "Studies have confirmed that IL-1β, IL-1α, IL-6, IL-8, IL-18 and their receptors are permanently expressed in malignant melanoma cells, suggesting that chronic inflammation exists during the melanoma development." (PMID 30149677, 2018). "Increased IL-6 blood levels in melanoma patients correlate with disease progression and lower response to chemotherapy." (PMID 29713020, 2018). "As an example of SFM-DR by CAFs, studies of the drug resistance of melanoma to chemotherapeutic agents have shown that CAFs assisted in metastasis and drug resistance by increasing the expression of IL-6, IL-8, MMP1, MMP2, and MMP972,73." (PMID 29403007, 2018).
melanoma (continued). "In a recent study, we found that the immobilized GPR56-specific CG4 antibody enhanced IL-6 production and migration ability of melanoma cells." (PMID 30135857, 2018). "Interleukin (IL-)1β, IL-6 and IL-8, for example, are known to be important drivers of cell proliferation and melanoma progression." (PMID 30591049, 2018). "Herein, it was found that PTX-treated MDA-MB-231 BCA and MDA-MB-435 melanoma cells showed upregulation of IL-6, IL-8 and XIAP expression compared to untreated cells." (PMID 29486738, 2018). "Application of antibodies blocking the IL-6 and IL-8 activity fully inhibits the melanoma cell migration in vitro." (PMID 29236046, 2017). "IL-10 has been shown to inhibit the production of IL-1, IL-6, IL-8, TNF-α and forced expression of IL-10 suppressed VEGF and MMP-9, secreted by tumor-associated macrophages in melanoma model." (PMID 29219852, 2017). "Ectopic expression of IRE1α and XBP1s in melanocytes and melanoma cells increased IL-6 levels and then activated intracellular STAT3 signaling, which was diminished by the addition of IL-6 antibodies." (PMID 28222747, 2017). "Our previous studies in melanoma patients have shown an IL-6 increase as a marker of immune system upregulation sustained by the keratinocytes that secrete this cytokine in order to enhance the T cells' antitumoral activity." (PMID 29318162, 2017). "Above all, IL-6 neutralization attenuated the enhanced proliferation of melanoma cells induced by the activation of the IRE1α-XBP1 branch, thus suggesting that anti-IL-6 antibody is a promising candidate for the clinical treatment of melanoma." (PMID 28222747, 2017). "Relative to the melanoma cells, in this case pretreatment with extract also significantly decreased the levels of IL-8, IL-6, MMP-2 and MMP-9." (PMID 28264501, 2017). "Further, IL-6 induces melanoma differentiation whereas IL-10 supports the enrichment of undifferentiated melanoma stem like compartment." (PMID 28137308, 2017). "IL-6 expression levels were determined in both melanocytes (HEMn-MP) and melanoma cells (Mel-RMu) overexpressing the spliced form of XBP1 (XBP1s)." (PMID 28222747, 2017). "Circulatory IL-6 was reported in both human and mice, showing serum IL-6 elevation correlated with poor prognosis in melanoma and progression towards metastasis." (PMID 29318162, 2017). "IL6 is known to be involved in the metastatic and invasion properties of melanoma, SCC of the skin and Head and Neck SCC." (PMID 28982115, 2017). "In our mouse model, IL-6 was found different in the male group versus female group upon melanoma cytostatic therapy, while drastically reduced in females, it was found increased in males." (PMID 29318162, 2017). "In vitro co-culture experiments show that CAFs promote migration and invasiveness of melanoma cells and such migration is dependent on IL-6 and IL-8 secretion." (PMID 29236046, 2017). "In agreement to these classical pathways, we have recently shown that IL-6 can induce p38α-MAPK activation in melanoma cells." (PMID 27191257, 2016). "In the next set of experiments, we employed a more feasible therapeutic approach by combining Box5 (a WNT5A antagonist) and a neutralising anti-IL-6 antibody to investigate the efficacy of such a combined treatment on melanoma cell migration and invasion." (PMID 27191257, 2016). "Together, these analyses and our cell line data suggest that WNT5A and IL-6 mRNA expression is poorly correlated in melanoma cells, although their increased expression is characteristic of an invasive melanoma cell phenotype." (PMID 27191257, 2016). "Increased expression and signalling of WNT5A and interleukin-6 (IL-6) have both been shown to promote melanoma progression." (PMID 27191257, 2016). "Apart from WNT5A, there are other regulators of melanoma cell invasion that promote metastasis; IL-6 is one of these regulators." (PMID 27191257, 2016).
melanoma (continued). "In turn, this leads to reduced expression and secretion of NF-κB downstream target molecules, including IL-1β, IL-6 and IL-8, which ultimately suppresses melanoma growth and metastasis." (PMID 27203220, 2016). "The data indicate that in melanoma IL-6 is mainly induced by CT and in glioblastoma by norm-fractionated RT." (PMID 28066420, 2016). "Similar to WNT5A, the pro-inflammatory cytokine IL-6 promotes melanoma cell invasion, and its increased expression is correlated with reduced overall patient survival." (PMID 27191257, 2016). "Several studies have highlighted the ability of either IL-6 or WNT5A to promote melanoma cell motility." (PMID 27191257, 2016). "Surprisingly, osteopontin and IL-6 formed a positive loop, which led to CXCLs production from melanoma cancer cells." (PMID 27049717, 2016). "Knockdown with anti-IL-6 siRNAs or treating WM852 melanoma cells with a neutralising anti-IL-6 antibody reduced WNT5A protein expression." (PMID 27191257, 2016). "Similar to the IL-6 level, the expression of the IL-6 receptor (IL-6R) also increases with melanoma progression, indicating an autocrine or paracrine function for IL-6 during melanoma progression." (PMID 27191257, 2016). "Functionally, we demonstrated that combined siRNA knockdown of WNT5A and IL-6 expression or the simultaneous inhibition of WNT5A and IL-6 signalling inhibited melanoma cell invasion more effectively than suppressing each factor individually." (PMID 27191257, 2016). "In melanoma cells DTIC was the main trigger to induce release of IL-6, in particular 48 h after treatment." (PMID 28066420, 2016). "In this analysis, we found elevated expression of both WNT5A and IL-6 transcripts in invasive melanoma cells." (PMID 27191257, 2016). "In melanoma cells CT was the main trigger for IL-6 release, while in glioblastoma cells it was norm-fractionated RT." (PMID 28066420, 2016). "Conversely, the silencing of WNT5A expression by WNT5A siRNAs or treating WM852 melanoma cells with Box5 (a WNT5A antagonist) significantly reduced IL-6 secretion." (PMID 27191257, 2016). "First, the HOPP algorithm revealed that the invasive phenotype of cultured melanoma cells was significantly correlated with increased expression of WNT5A or IL-6." (PMID 27191257, 2016). "More importantly, we demonstrated that the IL-6-induced p38α-MAPK activation promoted melanoma cell migration and invasion through increased WNT5A expression." (PMID 27191257, 2016). "Of these, we confirmed nuclear factor kappa B (NF-κB) subunit RelA, as a novel direct target of miR-7-5p in melanoma cells, such that miR-7-5p suppresses NF-κB activity to decrease expression of canonical NF-κB target genes, including IL-1β, IL-6 and IL-8." (PMID 27203220, 2016). "RASSF8 exerts its effect on melanoma via regulation of P65 expression and the downstream target IL-6, thereby controlling tumor cell growth, migration and invasion." (PMID 26334503, 2015). "Given that IL-6 positively regulated the Wnt5a expression through the p38α-MAPK pathway in melanoma, we draw the reasonable inference that CD146 probably drives melanoma cell motility through the CD146-IL-6-p38α-MAPK- Wnt5a-WRAMP pathway." (PMID 25685061, 2015). "On the basis of our previous findings we strongly propose a positive feedback loop whereby WNT5A regulates its own expression by indirectly regulating IL-6 in melanoma cells." (PMID 26393652, 2015). "Our recent study on melanoma cells demonstrated that IL-6 can regulate expression levels of WNT5A in a p38α MAPK-dependent manner, thereby regulating melanoma cell migration." (PMID 26393652, 2015). "One study, which attempted to identify a molecular signature in human RGP and VGP melanoma cell lines, found an invasion-specific signature that was characterized by the upregulation of genes including IL-6, IL-8, and MMP-1." (PMID 25798946, 2015).
melanoma (continued). "In the B16 mouse melanoma tumor model, silencing of A20 enhances the CpG-triggered induction of NFκB activity followed by elevated expression of IL-6, TNF-α and IL-12." (PMID 26327508, 2015). "Stimulation of melanoma cells and monocytes by lipopolysaccharide resulted in cytoplasmic translocation of hnRNPD from nucleus and reduced levels of IL-6, IL-10 and TNF-α following activation of MKP-1 (MAPK phosphatase-1)." (PMID 26318153, 2015). "Next to angiogenin and VEGF, IL-6 is another prominent example for a pro-angiogenic factor induced by NF-κB in melanoma." (PMID 26000250, 2015). "IL-1β, IL-6, and IL-8, found in the melanoma tumor microenvironment, are important drivers of cell proliferation and melanoma progression." (PMID 25798946, 2015). "In good agreement, the authors also demonstrated that Box-5 impaired IL-6-induced migration in melanoma cells." (PMID 26393652, 2015). "IL-6 treatment significantly increased anoikis resistance in all the melanoma cell lines as compared to untreated controls." (PMID 25216522, 2014). "Due to the fact that IL-6 mRNA levels remained unaffected in our study we believe that the mechanism behind WNT5A induced IL-6 release in malignant melanoma cells is Myd88/TLR2 independent." (PMID 24766647, 2014). "It had previously been reported that WNT5A expression was connected to the presence of the immunomodulatory and pro-angiogenic factor IL-6 in supernatants from malignant melanoma cells." (PMID 24766647, 2014). "One interesting study also outlined an IL-6-mediated angiogenic cytokine production and tumour growth pathway linked to STAT3 in B16 melanoma and MB49 bladder carcinoma cell lines." (PMID 25110397, 2014). "The role of paracrine factors such as angiogenic peptide basic fibroblast growth factor (bFGF) have been illustrated in different tumors including leukemia, and solid tumors such as IL-6 (interleukin 6) in melanoma or jagged 1 in colon cancer." (PMID 24424657, 2014). "We have demonstrated here that senescent melanoma cells secrete IL-6, IL-8 [CXCL8] and GRO [CXCL1, 2 and 3] in vitro and in vivo, which are associated with the pro-inflammatory response and recruitment of neutrophils and macrophages to senescent tumour cells." (PMID 23180582, 2013). "Interleukin-6 (IL-6) is a critical growth factor for melanoma cells, IL-6 can directly activate STAT3 phosphorylation through JAK family kinases." (PMID 23166634, 2012). "Harmine significantly inhibited the production of pro-inflammatory cytokines, namely TNF-α, IL-1β, IL-6 and GM-CSF by B16F-10 melanoma cell in culture." (PMID 21429205, 2011). "Upon co-culture with melanoma cells, the pro-angiogenic factors IL-8, IL-6, and IL-1β are up-regulated in neutrophils, synergistically promoting a microenvironment favorable for melanoma invasiveness." (PMID 24212647, 2011). "Another study investigating the role of Stat3 in immune evasion in human melanoma cells, has reported that Stat3 siRNA decreased the mRNA expression of IL-6, IL-10 and VEGF." (PMID 21122157, 2010). "Melanoma patients with high serum IL-6 have a shorter survival and a tendency to be resistant to IL-2 therapy." (PMID 24281094, 2010). "Malignant melanomas were supposed to harbour the human herpesvirus-type 8 (HHV-8) genome, as melanoma cells were reported to express interleukin-6 and a homologue of interleukin-6 was found in the HHV-8 genome." (PMID 10389979, 1999). "In addition, RSC-EXO reduced melanin production in α-MSH-stimulated B16F10 melanoma cells and suppressed the secretion of pro-inflammatory cytokines, including IL-1α, IL-6, and TNF-α, in LPS-stimulated RAW 264.7 macrophages." (PMID 42278464, 2026). "A preliminary in vitro assay showed that HLA-G may increase IL-6 secretion by leukocytes in the same way that plasma-derived LEVs from melanoma patients." (PMID 41268555, 2025).